ETNK2 (ethanolamine kinase 2)
Description:
Catalyzes the ATP-dependent phosphorylation of ethanolamine to phosphoethanolamine (By similarity). Highly specific for ethanolamine phosphorylation and does not exhibit choline kinase activity (By similarity).
Synonyms: EKI2; HMFT1716; FLJ10761
Tractability: No criterion of Open Targets' tractability assessment is met for any kind of drug.
Gene: Protein-coding gene on chromosome 1 (204,131,062 to 204,152,044, reverse strand). Ensembl gene ENSG00000143845.
Pathways (Reactome):
Metabolism: Synthesis of PE
Gene Ontology:
Molecular function: protein binding; ethanolamine kinase activity
Biological process: phosphatidylethanolamine biosynthetic process
Cellular component: cytoplasm; cytosol
Genetic constraint (gnomAD): Loss-of-function variants: 33 observed, 43.36 expected, observed/expected ratio (o/e) 0.76, 90% interval 0.58 to 1.02. The upper end of that interval is the gene's LOEUF score, 1.02, which puts it in group 4 of 6, group 1 being the genes least tolerant of losing a copy. Missense variants: 445 observed, 483.26 expected, observed/expected ratio (o/e) 0.92, 90% interval 0.85 to 1. Synonymous variants: 194 observed, 198.82 expected, observed/expected ratio (o/e) 0.98, 90% interval 0.87 to 1.1.
Homologues: Orthologues: dog ETNK2 (91% identical), rat Etnk2 (89% identical), chimpanzee ETNK2 (88% identical), mouse Etnk2 (87% identical), guinea pig ETNK2 (87% identical), macaque ETNK2 (87% identical), pig ETNK2 (84% identical), zebrafish etnk2 (59% identical), Drosophila melanogaster eas (43% identical), Caenorhabditis elegans ckc-1 (29% identical). Paralogues in human: ETNK1 (54% identical), CHKA (29% identical), CHKB (28% identical).
Diseases named in the same sentence as ETNK2 in open-access papers:
ETNK2 is named in the same sentence as 22 diseases in open-access papers, as found by Europe PMC text mining. Sharing a sentence is not in itself a finding about the gene and the disease. The quoted sentences say what the papers report.
gastric cancer (5 papers, 2021 to 2023). A primary or metastatic malignant neoplasm involving the stomach. "Higher expression of ETNK2 in gastric cancer is associated with a worse prognosis." (PMID 37046844, 2023). "On the other hand, ETNK2 in gastric cancer has an antiapoptotic effect, increases proliferation and migration, and causes metastasis of gastric cancer to the liver." (PMID 37046844, 2023). "The upregulation of ETNK2 enhances hepatic metastasis such as gastric cancer." (PMID 36176391, 2022). "Therefore, ETNK2 in gastric cancer is an oncogene, as it is in glioblastoma." (PMID 37046844, 2023).
breast carcinoma (2 papers, 2020 to 2024). "The accumulation of this metabolite was associated with an increased expression of ethanolamine kinase 2 (ETNK2) that converts ethanolamine to phosphoethanolamine in pancreatic and breast cancer cells." (PMID 39456684, 2024). "ETNK2 is significantly focally amplified in breast cancer tumors (Q = 7.6e−5) and located in a peak with 94 other genes." (PMID 33205077, 2020). "ADCK5, ETNK2, PSKH2, RPS6KC1, and SCYL3 are all significantly focally amplified in breast cancer samples as well but are not located in a peak region." (PMID 33205077, 2020).
laryngeal squamous cell carcinoma (2 papers, 2021 to 2023). A squamous cell carcinoma that arises from the larynx. "Only a few studies have found a link between ETNK2 and cancer, with one finding claiming that increased CpG methylation in the ETNK2 gene promoter is associated with radiotherapy resistance in laryngeal squamous cell carcinoma." (PMID 36866238, 2023).
lymph node metastasis (2 papers, 2021 to 2022). "Histological type (P<0.001), lymph node metastasis (P<0.001), and disease stage (P=0.011) were associated with high expression of ETNK2." (PMID 35069898, 2022). "High ETNK2 expression was significantly associated with vessel invasion, lymph node metastasis, and disease stages." (PMID 33531692, 2021). "We found that patients with high ETNK2 mRNA levels in clinical GC samples was significantly associated with vessel invasion, lymph node metastasis, and advanced disease stage with poor prognosis." (PMID 33531692, 2021). "ETNK2 overexpression was an independent high-risk predictor of PTC lymph node metastasis." (PMID 35069898, 2022). "Regression analysis indicated that the high expression of ETNK2 was closely related to lymph node metastasis." (PMID 35069898, 2022). "Patients with high levels of ETNK2 exhibited a higher incidence of the classical type and were more prone to lymph node metastasis and later disease staging." (PMID 35069898, 2022).
glioblastoma (1 paper, 2023). The most malignant astrocytic tumor (WHO grade IV). "Conversely, higher expression of ETNK2 in glioblastoma is associated with a worse prognosis for patients with this type of cancer." (PMID 37046844, 2023).
glioma (1 paper, 2018). A benign or malignant brain and spinal cord tumor that arises from glial cells (astrocytes, oligodendrocytes, ependymal cells). "The mean z-scores for CHKA and ETNK2 mRNA expression showed a significant reduction in IDHmut glioma samples relative to IDHwt (0.21 in IDHwt to − 0.16 in IDHmut, p < 0.0001 for CHKA and 0.69 in IDHwt to − 0.12 in IDHmut, p < 0.001 for ETNK2)." (PMID 29619216, 2018).
laryngeal carcinoma (1 paper, 2018). Carcinoma that arises from the laryngeal epithelium. "Increased methylation levels of promoters of TOP2A (DNA topoisomerase II alpha), PLXDC2 (plexin domain containing 2), ETNK2 (ethanolamine kinase 2), GFI1 (growth factor independent 1 transcriptional repressor), and IL12B (interleukin 12B) were detected in radioresistant laryngeal cancer cells." (PMID 29439529, 2018).
lung carcinoma (1 paper, 2021). "Elevated biosynthesis of PE in lung cancer tissue was supported by enhanced expression of the PE biosynthesis genes ETNK2 and EPT1 and decreased expression of the PC and PI biosynthesis genes CHPT1 and CDS2, respectively, in different subtypes of lung cancer in publicly available datasets." (PMID 33408336, 2021).
non-small cell lung carcinoma (1 paper, 2022). A group of at least three distinct histological types of lung cancer, including non-small cell squamous cell carcinoma, adenocarcinoma, and large cell carcinoma. "Phosphatidylethanolamine synthesis in non-small cell lung cancer is significantly enhanced by ETNK2, whereas reduced ETNK2 expression in prostate cancer results from the loss of TET2 targeted demethylation." (PMID 35873461, 2022).
Obesity (1 paper, 2020). Accumulation of substantial excess body fat. "Similarly, TT carriers of ETNK2-rs1106778 showed an increased risk of obesity when consuming a large amount of SSB, whereas C-allele carriers (CC + CT) did not." (PMID 32399287, 2020).
papillary thyroid carcinoma (1 paper, 2022). "To further determine the relationship between ETNK2 and papillary thyroid carcinoma, we performed an in vitro experiment." (PMID 35069898, 2022). "In our cell function experiments, we confirmed that ETNK2 promotes the clonal proliferation, migration, proliferation, apoptosis, and cell cycle arrest of papillary thyroid carcinoma." (PMID 35069898, 2022). "In our study, we found for the first time in a public database that expression of ETNK2 is highly upregulated in papillary thyroid carcinoma compared to control thyroid tissue." (PMID 35069898, 2022).
prostate carcinoma (1 paper, 2022). A carcinoma that arises from epithelial cells of the prostate gland. "ETNK2 is an ethanolamine kinase that has enhanced expression in gastric, non-small cell lung, and prostate cancers." (PMID 35873461, 2022).
thyroid cancer (1 paper, 2022). "In conclusion, this work aimed to determine the relationship between ETNK2 expression and its role in thyroid cancer proliferation, migration, invasion, apoptosis, and cell cycle arrest." (PMID 35069898, 2022). "In addition, western blotting suggested that ETNK2 is related to the HIPPO pathway and may activate the EMT pathway through the HIPPO pathway to promote the development of thyroid cancer." (PMID 35069898, 2022).
thyroid malignant tumours (1 paper, 2022). "At present, there is no literature concerning the relationship between ETNK2 and thyroid malignant tumours, so we investigated this relationship to explore new molecular markers of PTC." (PMID 35069898, 2022).
cancer (5 papers, 2020 to 2023). A tumor composed of atypical neoplastic, often pleomorphic cells that invade other tissues. "The ETNK2 gene is a novel molecular marker that provides insights into the role of survival risk in several cancers." (PMID 36866238, 2023). "ETNK2 suggests the significance of survival risk in some cancers and serves as a new molecular marker, but its role in PTC has not yet been elucidated." (PMID 35069898, 2022). "Because many anti-cancer drugs induce apoptosis, it is possible that ETNK2 is associated with drug resistance." (PMID 33531692, 2021). "Our results indicated that ETNK2 contributes, at least in part, to cancer progression via lymphatic systems." (PMID 33531692, 2021). "Cox-proportional hazard ratios on Tdark kinases and their CNAs reveal that SBK2, ETNK2, PSKH2, SCYL3, and NRBP2 are all significantly prognostic for survival across all cancers." (PMID 33205077, 2020). "Among them, CDH1, ETNK2, ADARB2, and RAB40C are found to be aberrantly methylated in different cancers." (PMID 32961999, 2020). "Initially, we conducted a pan-cancer study in which we searched the Gene Expression Profiling Interactive Analysis, the UALCAN, and the Human Protein Atlas databases to determine the expression level of the ETNK2 gene in KIRC." (PMID 36866238, 2023).
tumor (5 papers, 2018 to 2023). "We found the distinct infiltration levels of various tumor-infiltrating lymphocytes (TILs) are linked to varying levels of ETNK2 expression." (PMID 36866238, 2023). "The level of ETNK2 gene expression in KIRC tumor tissues was moderately positively linked to the degree to which immune cells such as neutrophils infiltrated the tumor." (PMID 36866238, 2023). "Stratification of GC patients based on ETNK2 mRNA level revealed significant associations between high ETNK2 tumour expression and both hepatic recurrence and worse prognosis." (PMID 33531692, 2021). "In IHC analysis, we found loss of ETNK2 expression in subcutaneous tumours from ETNK2 KO cells." (PMID 33531692, 2021). "We also found increased expression of cleaved caspase-3 and cleaved PARP in ETNK2 KO subcutaneous tumours by IHC analysis." (PMID 33531692, 2021). "According to the findings, the ETNK2 gene plays a crucial role in tumor growth." (PMID 36866238, 2023). "Patients identified to have high tumour expression of ETNK2 could undergo aggressive postoperative surveillance using enhanced MRI or ultrasonography to ensure early detection of hepatic recurrence." (PMID 33531692, 2021). "Furthermore, we found increased expression of cleaved caspase-3 and cleaved PARP in subcutaneous tumours from ETNK2 KO cells compared to those from a control MKN1 cells." (PMID 33531692, 2021). "We speculate that in PTC, ETNK2 may activate EMT through the HIPPO pathway, promoting tumour migration and proliferation." (PMID 35069898, 2022). "At 12 weeks after cell injection, the macroscopic appearance of liver specimens from mice injected with parental MKN1 cells revealed multiple tumour nodules, whereas none were detected in the livers of mice implanted with the ETNK2 KO cell line." (PMID 33531692, 2021). "Methylation of ETNK2, NTN1, and NUDT10 was increased in ERG-fusion negative tumors, which is concordant with the significant loss of TET2 expression in these tumor samples." (PMID 30917865, 2019). "We observed that mice bearing ETNK2 KO tumours emitted significantly weaker luminescence signals compared with the parental tumours, and no hepatic metastasis could be detected by MRI imaging." (PMID 33531692, 2021).
ETNK2 also shares sentences with these, for which no sentence is quoted: adenoma (2 papers); Alzheimer disease (1); lung adenocarcinoma (1); lung squamous cell carcinoma (1); periodontitis (1); renal cell carcinoma (1).